INHBB (inhibin subunit beta B)
Description:
Inhibins and activins inhibit and activate, respectively, the secretion of follitropin by the pituitary gland. Inhibins/activins are involved in regulating a number of diverse functions such as hypothalamic and pituitary hormone secretion, gonadal hormone secretion, germ cell development and maturation, erythroid differentiation, insulin secretion, nerve cell survival, embryonic axial development or bone growth, depending on their subunit composition. Inhibins appear to oppose the functions of activins. Activin B is a dimer of alpha and beta-B that plays a role in several essential biological processes including embryonic development, stem cell maintenance and differentiation, haematopoiesis, cell proliferation and wound healing. Signals through type I receptor ACVR1C, abundantly expressed in pancreatic beta cells, and type II receptors like ACVR2A or BMPR2. Upon ligand binding, these receptors phosphorylate intracellular signaling mediators SMAD2 and SMAD3, which form a complex with SMAD4, translocate to the nucleus, and regulate gene expression. Plays a crucial role in the induction of hepcidin by inflammation through activation of ACVR1C and subsequent phosphorylation of SMAD1/5/8. Regulates adipocyte lipid metabolism by decreasing non-esterified fatty acids and glycerol release and increases intracellular triglyceride content (By similarity). Stimulates wound healing by promoting cell migration and hair follicle regeneration through the JNK and ERK signaling pathways downstream of RHOA (By similarity). Inhibin B is a dimer of alpha and beta-B that plays a crucial role in the regulation of the reproductive system by inhibiting the secretion of follicle-stimulating hormone (FSH) from the anterior pituitary gland. Thereby, maintains reproductive homeostasis in both males and females. Acts as a more potent suppressor of FSH release than inhibin A (By similarity). Functions as competitive receptor antagonist binding activin type II receptors with high affinity in the presence of the TGF-beta type III coreceptor/TGFBR3L (By similarity).
Tractability: Antibody: its Gene Ontology location is reachable by antibodies, with high confidence; UniProt places it where antibodies can reach, with medium confidence; UniProt predicts a signal peptide or a membrane-spanning region.
Gene: Protein-coding gene on chromosome 2 (120,346,136 to 120,351,803, forward strand). Ensembl gene ENSG00000163083.
Subcellular location: Secreted
Subcellular location (Human Protein Atlas): Vesicles; Predicted to be secreted
Pathways (Reactome):
Signal Transduction: Antagonism of Activin by Follistatin; Signaling by Activin
Metabolism of proteins: Glycoprotein hormones
Gene Ontology:
Molecular function: protein binding; protein homodimerization activity; cytokine activity; hormone activity; host cell surface receptor binding; growth factor activity
Biological process: activin receptor signaling pathway; negative regulation of follicle-stimulating hormone secretion; negative regulation of hepatocyte growth factor production; positive regulation of follicle-stimulating hormone secretion; response to wounding; cell differentiation; cell surface receptor protein serine/threonine kinase signaling pathway; cellular response to insulin stimulus; cellular response to starvation; defense response; fat cell differentiation; negative regulation of insulin secretion; ovarian follicle development; positive regulation of ovulation; adhesion of symbiont to host cell; cellular response to calcium ion; cellular response to cAMP; cellular response to cholesterol; cellular response to interleukin-1; cellular response to leptin stimulus; cellular response to phorbol 13-acetate 12-myristate; cellular response to Thyroglobulin triiodothyronine; cellular response to thyroid hormone stimulus; female gonad development; male gonad development; and 5 more
Cellular component: perinuclear region of cytoplasm; extracellular region; cell periphery
Genetic constraint (gnomAD): Loss-of-function variants: 7 observed, 23.57 expected, observed/expected ratio (o/e) 0.3, 90% interval 0.17 to 0.56. The synonymous counts are far from expectation, so gnomAD's model fits this gene poorly and the ratio says little. Missense variants: 472 observed, 508.72 expected, observed/expected ratio (o/e) 0.93, 90% interval 0.86 to 1. Synonymous variants: 287 observed, 231.41 expected, observed/expected ratio (o/e) 1.24, 90% interval 1.12 to 1.37.
Homologues: Orthologues: chimpanzee INHBB (99% identical), macaque INHBB (99% identical), dog INHBB (98% identical), rat Inhbb (98% identical), mouse Inhbb (97% identical), pig INHBB (97% identical), guinea pig INHBB (88% identical), rabbit INHBB (71% identical), tropical clawed frog inhbb (69% identical), zebrafish inhbb (66% identical), zebrafish INHBB (49% identical). Paralogues in human: INHBA (43% identical), INHBC (33% identical), INHBE (29% identical), BMP8B (22% identical), BMP6 (22% identical), BMP8A (22% identical), GDF11 (21% identical), MSTN (21% identical), BMP10 (20% identical), BMP4 (20% identical), BMP7 (20% identical), GDF2 (20% identical), and 19 more.
Diseases named in the same sentence as INHBB in open-access papers:
INHBB is named in the same sentence as 78 diseases in open-access papers, as found by Europe PMC text mining. Sharing a sentence is not in itself a finding about the gene and the disease. The quoted sentences say what the papers report.
breast carcinoma (10 papers, 2011 to 2023). "rs12468790 (INHBB) was also associated with breast cancer but in a direction opposite to its effect on MD." (PMID 29665850, 2018). "Stratified analyses by breast cancer subtype revealed that the association of rs12468790 (INHBB) with breast cancer was stronger for ER-negative (OR [95% CI] per minor allele increase = 0.93 [0.91–0.95], P = 1.5 × 10− 9) than ER-positive tumors (OR [95% CI] = 0.98 [0.96–0.99], P = 3.8 × 10− 3)." (PMID 29665850, 2018). "The stronger association of this variant with ER-negative than ER-positive breast cancers may also point to alternative mechanisms linking INHBB to breast cancer than a causal path acting through mammographic dense tissue." (PMID 29665850, 2018). "Considering these results, we stimulated SUM159-LM1 breast cancer cells with either recombinant activin B, a homodimer of INHBB, or recombinant SCGB3A1, and this also induced sphere formation by cancer cells." (PMID 35469015, 2022). "In this study, we identified three novel MD loci at genome-wide significance (percent dense volume [HABP2] and absolute dense volume [INHBB, LINC01483]), of which two (HABP2, LINC01483) represent putative novel breast cancer susceptibility variants." (PMID 29665850, 2018). "Through correlation analysis of gene expression profiles between candidate genes and miR-148a in the TCGA breast cancer patient database, we further narrowed down targets of miR-148a to four genes, INHBB, PIK3C2B, WNT1 and NRP1." (PMID 26967387, 2016). "However, INHBB was downregulated in some cancers, such as breast cancer, cervical cancer, and leukemia." (PMID 33083477, 2020). "The association of rs12468790 (INHBB) with the absolute dense volume, however, was not consistent with the MD-breast cancer risk association." (PMID 29665850, 2018). "Of note, a variant (rs4849887) downstream of the INHBB gene but not in linkage disequilibrium (LD) with rs12468790 is an established breast cancer susceptibility variant." (PMID 29665850, 2018). "INHBB was closely correlated with cancer-promoting signalling pathways, including the TGF-β signalling pathway, focal adhesion, breast cancer, and prostate cancer, which have been studied before." (PMID 36913138, 2023). "Together, these results suggest that INHBB and SCGBA1 promote stem cell properties and aggression in breast cancer cells." (PMID 35469015, 2022). "The results suggest a putative role for INHBB and SCGB3A1 in the promotion of stem cell properties in breast cancer cells." (PMID 35469015, 2022). "Similar results were observed in another breast cancer cell line MCF-7, where miR-218 also upregulated INHBA but downregulated INHBB expression." (PMID 30348200, 2018). "The other three loci (ZNF703, INHBB, and AREG) have strong links to breast cancer, estrogen regulation, and breast development." (PMID 22747683, 2012). "The sphere-forming ability of breast cancer cells was markedly increased when treated with CM containing INHBB or SCGB3A1, but not with OPG or LAMA1." (PMID 35469015, 2022).
colorectal cancer (8 papers, 2009 to 2025). A primary or metastatic malignant neoplasm that affects the colon or rectum. "Leading edge analysis showed that INHBB is closely associated with these signaling pathways, indicating that INHBB or activin B might be involved in the regulation of colorectal cancer by mediating these cancer-promoting pathways and their downstream targets." (PMID 33083477, 2020). "To further validate the impact of INHBB on the proliferative capacity of colorectal cancer cells, we conducted colony formation assays." (PMID 39850875, 2024). "INHBB expression has been found to be upregulated in colorectal cancer tissues and to be positively related to stromal and immune scores." (PMID 34421995, 2021). "In the present study, we first found that INHBB is highly expressed in colorectal cancer compared to normal adjacent tissue by analysis of data in TCGA and GEO databases and finally validated it in our cohort." (PMID 33083477, 2020). "INHBB expression was elevated in various cancers, such as brain cancer, colorectal cancer, esophageal cancer, head and neck cancer, and kidney cancer." (PMID 33083477, 2020). "In recent years, only some studies research the potential mechanisms of elevated INHBB expression in colorectal cancer and have shown that hypermethylation of the INHBB promoter is found in colorectal cancer." (PMID 33083477, 2020). "The study is aimed at exploring the clinical significance of INHBB in patients with colorectal cancer (CRC) by bioinformatics analysis." (PMID 33083477, 2020). "Real-time PCR and analyses of Oncomine, Gene Expression Omnibus (GEO), and The Cancer Genome Atlas (TCGA) databases were utilized to evaluate the INHBB gene transcription level of colorectal cancer (CRC) tissue." (PMID 33083477, 2020). "The three CpG islands associated with the promoter region of the genes EN1, SCTR and INHBB mapping to 2q14.2 have been identified earlier to be hypermethylated in colorectal cancer." (PMID 19384295, 2009). "However, few studies evaluated the relationship between INHBB and clinical features in patients with colorectal cancer, especially for prognosis." (PMID 33083477, 2020). "The mechanisms of INHBB in colorectal cancer have been rarely explored." (PMID 33083477, 2020). "Additionally, Gene Set Enrichment Analysis (GSEA) was performed to evaluate the gene ontology (GO) and signaling pathways of INHBB involved in colorectal cancer." (PMID 33083477, 2020). "INHBB may be a novel target for individualized treatment of colorectal cancer." (PMID 33083477, 2020). "Overexpression of INHBB is positively correlated with poor OS and DFS, and INHBB is an independent prognostic factor for colorectal cancer." (PMID 33083477, 2020).
gastric cancer (6 papers, 2009 to 2025). A primary or metastatic malignant neoplasm involving the stomach. "INHBB promotes gastric cancer (GC) by reprogramming fibroblasts into cancer-associated fibroblasts (CAFs) and activating the NF-κB pathway, which enhances gastric cancer cell proliferation, migration, and invasion." (PMID 39850875, 2024). "INHBA and INHBB showed similar correlations with survival in gastric cancers, specifically HER2+, and renal papillary cell carcinoma." (PMID 33819300, 2021). "IL-1β activates transcription factor p65 of gastric cancer to up-regulate INHBB expression." (PMID 37858201, 2023). "In addition we selected two genes potentially inactivated by nonsense mutation which were located outside deleted areas, but showed high log2 ratios and no known splice variants (CSTA for the GP202 and INHBB for the IPA220 gastric cancer cell lines)." (PMID 19563644, 2009).
nasopharyngeal carcinoma (5 papers, 2020 to 2024). A carcinoma arising from the nasopharyngeal epithelium. "Indeed, high Activin B levels, a homodimer of INHBB, have been associated with a higher risk of metastasis in oral squamous cell carcinoma but, INHBB expression was more recently associated with an inhibition of cell migration in nasopharyngeal carcinomas." (PMID 33291363, 2020). "The levels of INHA and INHBB in nasopharyngeal cancer patients were lower than those in healthy people, and the levels in stage III + IV patients were lower than those in stage I + II patients." (PMID 38847724, 2024). "INHBB could suppress anoikis resistance and migration of nasopharyngeal carcinoma cells by the TGF-β signaling pathway." (PMID 38663918, 2024). "INHBB reduces the phosphorylation of Smad2/3 to inhibit EMT, indicating that INHBB may suppress the AR and migratory capacity of nasopharyngeal carcinoma (NPC) cells through the TGF-β/Smads signaling pathway." (PMID 39029056, 2024).
colon cancer (4 papers, 2019 to 2026). "However, research on the mechanisms of INHBB in colon cancer is relatively limited." (PMID 39850875, 2024). "In this work, we retrospectively identified four bone metastasis-related genes (INHBB, RBP7, RTN2, and ATOH1) and constructed a gene expression signature model for colon cancer patients by bioinformatic analysis." (PMID 34421995, 2021).
prostate carcinoma (4 papers, 2020 to 2023). A carcinoma that arises from epithelial cells of the prostate gland. "The Yu dataset showed a 1.59-fold increase (p < 0.0001) in INHBB expression in prostate carcinoma compared to healthy prostate." (PMID 36612143, 2022). "The Luo dataset also showed increased INHBB expression (fold change = 1.630) in prostate carcinoma when compared to benign prostatic hyperplasia (BPH; p = 0.024)." (PMID 36612143, 2022). "INHBB is upregulated and exerts tumorigenic activity in a variety of malignant tumors ranging from oral cancer to endometrial cancer, prostate cancer, and thyroid cancer." (PMID 34898475, 2021). "INHBB or activin B has been reported to be overexpressed in various malignant tumors and plays essential roles in tumor proliferation, invasion, and migration, such as oral cancer, endometrial cancer, prostate cancer, renal clear cell carcinoma, and thyroid cancer." (PMID 33083477, 2020).
endometrial cancer (3 papers, 2020 to 2024). Primary or metastatic malignant neoplasm involving the endometrium (mucous membrane that lines the endometrial cavity). "For example, INHBB expression is significantly elevated in endometrial carcinoma tissues and enhances cancer cell invasion by activating the SMAD2/3 and integrin β3 signaling pathways." (PMID 39850875, 2024). "INHBB and activin B are highly expressed in endometrial cancer, and activin B promotes cell adhesion, migration, and invasion via the SMAD2/3/integrin β3 signaling pathway." (PMID 33083477, 2020).
gout (3 papers, 2015 to 2024). A condition characterized by painful swelling of the joints, which is caused by deposition of urate crystals. "As expected, most of the urate loci are also risk factors for gout, with only four loci (INHBB, HNF4G, UBE2Q2, and BCAS3) yet to be formally associated with gout at a nominal level of significance." (PMID 25889045, 2015). "None of the variants of the known gout and hyperuricemia-related genes were co-segregated with the disease phenotype in this family, including ABCG2, SLC2A9, SLC22A11, SLC22A12, SLC17A1, SLC17A3, PDZK1, and INHBB." (PMID 39433541, 2024).
Infertility (3 papers, 2020 to 2024). "Men with polymorphisms in INHBB anatomically normal genitalia with infertility." (PMID 39639036, 2024). "INHBB was also identified and is considered a candidate marker gene for infertility in domestic animals." (PMID 32610571, 2020). "We found evidence at non-hormonal, pleiotropic, infertility loci for recent directional selection (EBAG9) and balancing selection (GREB1, INHBB, PCDH15)." (PMID 38562841, 2024).
male infertility (3 papers, 2017 to 2025). The inability of the male to effect fertilization of an ovum after a specified period of unprotected intercourse. "This suggests that they may serve as a valuable platform for elucidating the mechanisms by which semaglutide inhibits INHBB secretion, as well as for facilitating rapid and personalized modeling for male infertility and drug screening." (PMID 39990223, 2025). "Considering that INHBB may be used as a marker of spermatogenesis function and male infertility, our results strengthen the need of regulations that guarantee a high level of protection of human health." (PMID 28628672, 2017).
metabolic syndrome (3 papers, 2009 to 2025). A cluster of metabolic risk factors for CARDIOVASCULAR DISEASES and TYPE 2 DIABETES MELLITUS. "We therefore examined ALK7 and INHBB expression in relation to obesity and components of the metabolic syndrome." (PMID 19275893, 2009). "INHBB produced in adipocytes may play a role in the metabolic syndrome, since it was demonstrated that its expression is high in human adipocytes, reduced by weight loss, and correlates with factors implicated in metabolic disease." (PMID 28628672, 2017). "There were highly significant differences in the expression of both ALK7 and INHBB in lean and obese subjects and ALK7 and INHBB expression correlated with several indicators of the metabolic syndrome." (PMID 19275893, 2009).
Obesity (3 papers, 2009 to 2024). Accumulation of substantial excess body fat. "We find two independent associations with size flanking the gene INHBB, which has connections to estrogen regulation, obesity, and uterine cancer." (PMID 22747683, 2012). "This idea is supported by our observation that both INHBB and ALK7 expression are highly regulated by obesity and the expression levels correlate with metabolic parameters." (PMID 19275893, 2009).
oral squamous cell carcinoma (3 papers, 2020 to 2025). "Lastly, INHBB overexpression has been found to be associated with advanced clinical staging and metastasis in oral squamous cell carcinoma (OSCC) patients." (PMID 39941730, 2025).
renal fibrosis (3 papers, 2023 to 2025). A final common manifestation of a wide variety of chronic kidney diseases characterized by glomerulosclerosis and tubulointerstitial fibrosis. "Inhibition of INHBB can block the activation of mesenchymal fibroblasts and ameliorate renal fibrosis, which can be promoted by prolonged inflammation." (PMID 40705171, 2025). "Activin B is known as a member of TGF-β family that exists as an INHBB homodimer and plays an important role in renal fibrosis and skin scar hyperplasia." (PMID 37858201, 2023). "Further, inhibition and overexpression models of INHBB regulated renal fibrosis." (PMID 37365616, 2023).
thyroid cancer (3 papers, 2010 to 2021). "A significant inverse correlation was observed in the thyroid cancer samples for the L/R pair INHBB/ACVR1 (P<0.05), but not in the normal samples." (PMID 20877637, 2010). "Furthermore, other L/R pairs identified in our analysis, namely INHBB/ACVR1 and TNC/ANXA2, have been shown to be involved in invasiveness of other solid tumors, and as they have not yet been studied in thyroid cancer, warrant further investigation in this context." (PMID 20877637, 2010).
bladder cancer (2 papers, 2025). "In this study, we found that high INHBB expression correlates with poor prognosis in bladder cancer patients, a finding consistent with previous reports." (PMID 41153362, 2025).
cervical cancer (2 papers, 2020 to 2021). A primary or metastatic malignant neoplasm involving the cervix. "INHBB in contrast was mostly expressed in renal clear cell and hepatocellular carcinomas, which differs from renal papillary cell carcinoma and cervical cancer (p < 0.0001)." (PMID 33819300, 2021).